SGK1 (serum/glucocorticoid regulated kinase 1)
Diseases named in the same sentence as SGK1 in open-access papers (continued):
Sharing a sentence is not in itself a finding about the gene and the disease.
cancer (continued). "An increasing amount of scientific evidence has confirmed the therapeutic potential of SGK1 in human cancer, and a critical review is necessary." (PMID 33542904, 2020). "As evidence of the relevance of SGK1 in cancer increases, more inhibitors are expected to be developed for testing in the clinics." (PMID 33266470, 2020). "Ultimately, more studies are necessary to both elucidate the role of SGK1 as a regulator of immune cell differentiation and to investigate its potential as target to improve cancer immunotherapy." (PMID 33266470, 2020). "Consistent with this, it has been reported that SGK1 is essential for the invasion and metastasis of different human cancers." (PMID 33542904, 2020). "Although SGK1 plays multiple roles in cancer initiation, progression, metastasis, and treatment response in humans, its expression is modulated by various factors, including a multitude of stimuli, such as growth factors, mineralocorticoids, and cytokines." (PMID 33542904, 2020). "Due to the multiple functions of SGK1 in human cancer, the downstream target genes and relevant signaling pathways regulated by SGK1 interweave into a huge signaling network." (PMID 33542904, 2020). "The Heterogeneous nuclear ribonucleoprotein M (HNRNPM) binds to Rictor in the mTORC2 complex to enhance activation of AGC kinases, including SGK1, at least in muscle, but this protein is also involved in cancer invasion and metastasis." (PMID 29301334, 2018). "Taken together, this study unveils a novel mechanism in which SGK1 functions as a tumor metastasis-promoting gene and highlights how co-targeting SGK1 and autophagy restrains cancer progression due to the amplified antimetastatic effects." (PMID 29609629, 2018). "Our study also demonstrates the functional significance of its upregulation in metastatic PCa, and presents a novel combination therapy regimen that co-targeting SGK1 and autophagy restrains cancer progression due to the amplified antimetastatic effects." (PMID 29609629, 2018). "mTORC2, SGK1 and oncogenesis: therapeutic resistance is one of the major obstacles in the effective treatment of cancer patients, of which alkylating chemotherapy is often the standard of care." (PMID 29301334, 2018). "RANBP1, in turn, is regulated by the serum- and glucocorticoid-regulated kinase 1 (SGK1), a serine/threonine kinase that plays a key role in cancer signal transduction." (PMID 29340013, 2017). "In previous work, we showed that cancer cells displaying increased SGK1 activity, and hence increased RANBP1 levels, become less sensitive to the effects of the microtubule-stabilizing agent paclitaxel." (PMID 29340013, 2017). "SGK1 participates in many cellular pathways but has gained significant attention in the field of molecular oncology due to its role in several cancer cell pathways." (PMID 26841718, 2016). "Taken together, all these lines of evidence point to SGK1 as a key element in the development and/or progression of human cancer." (PMID 26908461, 2016). "Targeting either PDK1 or SGK1 restores the sensitivity of these resistant cancer cells to PI3Kα inhibition." (PMID 27451907, 2016). "This is because of the reported over-expression of SGK1 in carcinoma cells relative to normal cells." (PMID 26841718, 2016). "Clearly, acute treatment of cancer cells with rapamycin inhibits mTORC2 assembly accompanied with suppression of SGK1 S422 phosphorylation and increase of Akt S473 phosphorylation." (PMID 25797247, 2015). "Although more exhaustive toxicity studies of SI113 are needed, from a theoretical point of view, SGK1 inhibition is predicted to be quite safe in normal cells, yet is expected to be powerful in inhibiting proliferation and survival in cancer cells." (PMID 26462020, 2015). "Previous work has shown that treatment of cancer cell lines with dexamethasone promotes cell survival, an effect that is counteracted by knockdown of SGK1." (PMID 23581296, 2013).
cancer (continued). "It would be fascinating to evaluate the efficacy of a dual Akt/SGK inhibitor at suppressing growth of cancer cells exhibiting elevated SGK1 activity." (PMID 23581296, 2013). "Overexpression of SGK1 promotes tumor cell proliferation and migration while inhibiting induced apoptosis in cancer, suggesting a potential role for SGK1, and by extension SGK1-OT1, in promoting cell survival and proliferation—traits characteristic of cancer cells." (PMID 38600449, 2024). "GR activation also acts via the induction of serum- and glucocorticoid-induced kinase-1 (SGK1) upregulation, which is a significant contributor to many cancers, including triple-negative breast cancer (TNBC), where it contributes to GR potentiation of metastasis and proliferation." (PMID 37970210, 2023). "SGK1 stimulates the migration of vascular smooth muscle cells, cancer cells, and platelets." (PMID 37371111, 2023). "Increasingly, important roles for SGK-1 have been proposed in cancer biology." (PMID 37954869, 2023). "In several cancers, SGK1 has been identified as a tumor-promoting gene and a key prognostic factor." (PMID 37371111, 2023). "Thus, our results provide insight into a molecular pathway that enables SGK1 to gain phosphorylation and catalytic activity and promote cell survival, potentially diminishing the efficacy of cancer treatments." (PMID 37343701, 2023). "Misregulation of SGK1 functions can lead to diseases like hypertension, inflammation, fibrosis, stroke, thrombosis, diabetes Liddle syndrome, autoimmune disorders, pre-cancerous chronic diseases, and of course, cancer." (PMID 35625991, 2022). "SGK1 is involved in the development of almost all tumors and may function as a potential biomarker for cancer diagnosis and prognosis." (PMID 35711939, 2022). "High expression of SGK1 mediates resistance to PI3K inhibition in cancer cells where suppression of SGK1 or dual suppression of AKT/SGK1 might be useful for treatment." (PMID 35393773, 2022). "Over the last decade or more, the role of SGK1 in cancer has been demonstrated by several studies." (PMID 36457711, 2022). "Driven by the frequently increased expression level of SGK1 in pathologies, particularly in cancer and T cell‐mediated disorders, we sought to identify post‐translational processes and interacting proteins that modulate the abundance of SGK1 in cells and in mouse tissues." (PMID 35393773, 2022). "We examined a range of mutations and characterized their deleterious impact on the structure and function of SGK1, which may contribute to disease development and progression, such as cancer and neurodegeneration." (PMID 34805284, 2021). "Therefore, SGK1 seems to be an indicator of a good or bad prognosis for cancer patients, depending on the tumor type." (PMID 33542904, 2020). "Abnormal expression of SGK1 has been found in tissue and may hopefully become a useful indicator of cancer progression." (PMID 33542904, 2020). "In this review, we focus on the diagnostic and prognostic value of SGK1 in human cancer, which has not yet been critically reviewed elsewhere." (PMID 33542904, 2020). "Therefore, we can conclude that SGK1 governs key processes during the development of various cancer types." (PMID 33542904, 2020). "Expression pattern of SGK1 in different types of human cancer." (PMID 33542904, 2020). "In addition, SGK1 was detected to play a key role in the development of resistance to cancer chemotherapy in NSCLC patients." (PMID 33542904, 2020). "SGK1 has been shown to play a role in this process, since its inhibition, by either GSK650394 or SGK1 shRNA, may induce G2/M arrest, apoptosis, and autophagy through the mTOR-FoxO3a pathway in other human cancers." (PMID 33266470, 2020). "In a perspective of cancer treatment, an interesting area of investigation in relation to the potential therapeutic effects provided by targeting of SGK1 is offered by the control exerted by this kinase on a variety of channels involved in ion and nutrient absorption." (PMID 33266470, 2020).
cancer (continued). "SGK1 is considered a canonical factor affecting the expression and signal transduction of multiple genes involved in the genesis and development of many human cancers." (PMID 33542904, 2020). "Although several SGK1 inhibitors have paved the way for novel therapeutic interventions in the future, the prospects for clinical application of these inhibitors in cancer therapy are vague, which means that more preclinical studies, especially on toxicity and safety, should be conducted." (PMID 33542904, 2020). "SGK1 determines cancer cell proliferation or cell apoptosis in various tumors." (PMID 33542904, 2020). "Despite the role of SGK1 in cancer has been widely studied, its role and molecular regulation mechanism in tumor autophagy and metabolism need to be further investigated, especially the key downstream effector molecules and possible signaling pathways of SGK1 modulating autophagy and metabolism." (PMID 33542904, 2020). "SGK1 is involved in the development of almost all tumors and may function as a promising biomarker for cancer diagnosis and prognosis." (PMID 33542904, 2020). "Aberrant expression of SGK1 is closely related to the clinical characteristics of human cancer." (PMID 33542904, 2020). "All these investigations indicate that SGK1 could be a promising therapeutic target for overcoming radio-resistance in human cancer." (PMID 33542904, 2020). "It is, then, no surprise that SGK1 has been implicated in a variety of diseases, including in different types of human cancer." (PMID 33266470, 2020). "A growing number of investigations indicate that SGK1 has critical roles in tumorigenesis, cancer cell proliferation and apoptosis, cancer cell invasion and migration, cancer cell autophagy, cancer metabolism, therapeutic resistance, and the tumor microenvironment." (PMID 33542904, 2020). "Overall, SGK1 can regulate multiple downstream effector molecules related to apoptosis, cell growth and cell cycle through transcriptional regulation and/or phosphorylation, thus participating in the modulation of cancer growth." (PMID 33542904, 2020). "However, profiling of cancers for developing PI3K pathway resistance is likely to be an effective way of identifying which particular patient cohorts will be predisposed to SGK1-mediated resistance that could be treated with additional drugs that target mTORC2/SGK1." (PMID 29301334, 2018). "Although the weight of evidence supports the importance of SGK1 in cancer, exceptions do occur." (PMID 29301334, 2018). "Although the role and function of SGK1 were extensively studied in cancer, mainly focusing on tumor growth (e.g., cell proliferation, apoptosis and cell cycle arrest), little is known about the potential role of SGK1 in cancer metastasis." (PMID 29609629, 2018). "Consistent with this, SGK1 down-regulation sensitizes cancer cells to this drug." (PMID 29340013, 2017). "We assume that SGK1 may represent a promising therapeutic target for the eradication of hypoxic cancer cells." (PMID 27251632, 2016). "Moreover, we provide evidence supporting the essential and limiting role of SGK1 in cancer cell survival." (PMID 26908461, 2016). "Since SGK1 acts as a critical regulator in both these pathways, we consider that SGK1 overexpression may also have a central role in cancer." (PMID 26462020, 2015). "In future work it would be important to gauge whether the cancers most responsive to Akt inhibitors do indeed possess low levels of SGK1 protein/mRNA." (PMID 23581296, 2013). "SGK1 expression is also markedly induced by many steroid hormones, including the glucocorticoid dexamethasone, that are routinely used to reduce swelling in cancer patients." (PMID 23581296, 2013). "This raises the possibility that administration of steroid hormones to cancer patients receiving Akt inhibitors might have the potential to induce SGK1 in tumour cells and thereby induce resistance to Akt inhibitors." (PMID 23581296, 2013).
cancer (continued). "Finally, it would be of immense interest to explore the therapeutic utility of SGK1 inhibitors or dual Akt/SGK1 inhibitors in treating Akt-resistant cancer cells possessing elevated SGK1." (PMID 23581296, 2013). "As the DNA damage response operates in many cancer cells and is further induced by chemotherapies, the findings of this study could have significant implications for the development of novel cancer therapies targeting SGK1." (PMID 37343701, 2023). "Moreover, they suggest that SGK1 could mediate the key role of mTORC2 in de novo lipid synthesis in mammals and in cancer cells." (PMID 33939875, 2021). "In addition, SGK1 acts as a prognostic factor for cancer patient survival." (PMID 33542904, 2020). "Although the exact reason why SGK1 expression in cancer in the intestinal system is downregulated remains unclear, it has been postulated to most likely be due to transcriptional repressors acting on the SGK1 promoter." (PMID 33542904, 2020). "Moreover, SGK1 serves as a prognostic factor for the survival of cancer patients." (PMID 33542904, 2020). "Furthermore, to further clarify the roles and mechanisms of SGK1 in cancer, we systematically discuss whether SGK1 is an oncogene or a cancer suppressor by backtracking and summarizing the studies covering cells, cancer tissues and biofluids." (PMID 33542904, 2020). "In addition, SGK1 is commonly perceived to be a new drug target candidate for cancer treatment." (PMID 33542904, 2020). "Therefore, anti-cancer therapies that target SGK1 may have the additional beneficial effect of increasing pools of Th1 cells to enhance adaptive immunity-mediated anti-tumour responses." (PMID 29301334, 2018). "However, the functions and underlying mechanisms of SGK1 involved in invasion and metastasis regulation have not yet been investigated in cancer." (PMID 29609629, 2018). "Despite SGK1 has been identified and characterized as a tumor-promoting gene, the functions and underlying mechanisms of SGK1 involved in metastasis regulation have not yet been investigated in cancer." (PMID 29609629, 2018). "Thus, we hypothesized SGK-1 inhibition may also affect migration and invasion of cancer cells, thereby potentially improving the outcome." (PMID 25485633, 2014). "Indeed, by promoting induction of SGK1, steroid treatment could have the potential to promote proliferation of all cancers." (PMID 23581296, 2013). "To prove this hypothesis, we investigated whether SGK1 knockdown could affect cancer properties." (PMID 24185040, 2013). "Although small, these differences affected important signaling pathways (NGF-stimulated transcription, IL-10 signaling, PERK activity) and cancer genes (CBFA2T3, ETV4, FGFR1, GLI1, SGK1, and STAT3)." (PMID 38968069, 2024). "Like PDPN, serum/glucocorticoid-regulated kinase 1 (SGK1, lfc = −2.86), listed among the top 10 genes downregulated by QUE pre-treatment, is known to play a crucial role in tumourigenesis and cancer progression." (PMID 37755981, 2023). "Silencing of serum/glucocorticoid regulated kinase 1 (SGK1) disrupts the transcriptional YAP/TEAD4 complex, leading to the suppression of cancer cell growth and migration in vivo and in vitro." (PMID 35602596, 2022). "Through the mechanisms described here, such treatment is expected to decrease SGK1 abundance, potentially contributing to the improved response to PI3K inhibitors in cancer cells and to lessen activation of proinflammatory pathways in immune cells." (PMID 35393773, 2022). "SGK1 knockdown resulted in FOXO3a dephosphorylation and restored LC3-mediated autophagy formation, subsequently inhibiting the growth of cancer cells." (PMID 36457711, 2022). "The cancer-related genes BCL6, FANCC, PICALM and SGK1 were included among the target genes of the 64 TFBSs." (PMID 34316701, 2021). "CD4+CD45RO+ T cells in the lesional blood highly expressed genes relating to cancer progression and CTCL pathogenesis: RGS1, RDH10, HES1, DNAH9, ANK2, and SGK1 16–25." (PMID 34608214, 2021).
cancer (continued). "SGKs, which consist of three isoforms, SGK1, SGK2, and SGK3, are critical mediators of AKT-independent signaling downstream of PDK1 and mTORC2 in cancer." (PMID 33960177, 2021). "Surprisingly, this regulatory corepressive function of MTA1 was lost under hypoxia, allowing enhanced SGK1 expression and engaging the MTA1-SGK1 axis for the benefit of cancer cell survival." (PMID 33542904, 2020). "Therefore, SGK1 appears to be a malevolent player in the stress response to chemical and radio-therapeutics and might be responsible for a selective advantage that favors uncontrolled cancer progression and selection of the most aggressive clones." (PMID 33542904, 2020). "SGK1, which is activated by 3-phosphoinositide dependent kinase-1 (PDK1), contributes to the maintenance of residual mTORC1 activity and cancer cell growth through direct phosphorylation and inhibition of tuberous sclerosis 2 (TSC2)." (PMID 33542904, 2020). "Simultaneously, SGK1 restrained the production of interferon-γ (IFN-γ) by increasing the expression of the long isoform of the transcription factor TCF-1, thus promoting cancer growth." (PMID 33542904, 2020). "All these investigations indicate that miRNAs are the main epigenetic regulators to repress SGK1 expression via targeting its 3’-UTR, thus affecting the occurrence and progress of cancer." (PMID 33542904, 2020). "However, it has been proposed that SGK1 might, at least in part, promote cancer proliferation, differentiation, migration, invasion, and resistance to alkylating chemotherapy through the activation of its best characterized downstream target, N-myc downstream regulated gene 1 (NDRG1)." (PMID 33266470, 2020). "For example, AKT-inhibitor (AZD5363 and MK-22060) resistant cancer cell lines show increased NDRG1 phosphorylation, demonstrating that SGK1 can compensate for PI3K pathway inhibition." (PMID 29301334, 2018). "Given the potential link between SGK1, NDRG1 phosphorylation and cancer cell migration we used siRNA to deplete NDRG1 in MDA-MB-231 cells and then treated them with SGKi." (PMID 28545025, 2017). "Further data also point out the effect of the SGK1 kinase inhibitor SI113 in restraining in vitro and in vivo proliferation in several cancer cells, including GBM cells." (PMID 29340013, 2017). "Our previous work showed that the effectiveness of the spindle poison paclitaxel in inhibiting cancer cell growth was dependent on the expression of RANBP1, a regulatory target of the serine/threonine kinase SGK1." (PMID 29340013, 2017). "show that PDK1 activates SGK1 to phosphorylate and inhibit TSC2, contributing to maintenance of mTORC1 activity and resistance of PIK3CA-mutant cancer cells to PI3Kα inhibition." (PMID 27451907, 2016). "SGK1 is regulated by insulin, IGF-1, cAMP, glucocorticoids and IL-2 and transduces survival signals in normal and cancer cells." (PMID 26462020, 2015). "In contrast, in the cancer cell lines displaying high levels of SGK1, we find that NDRG1 phosphorylation is insensitive to Akt inhibitors and knockdown of SGK1 inhibits NDRG1 phosphorylation." (PMID 23581296, 2013). "It is well documented that NDRG1 is phosphorylated at multiple sites by serum- and glucocorticoid-induced kinase 1 (SGK1), which further primes NDRG1 for subsequent phosphorylation by glycogen synthase kinase 3 (GSK3), through which it demonstrates its anti-cancer properties." (PMID 38983911, 2024). "Several glucocorticoid-inducible proteins play important roles in pathogenesis of some cancers but their status and roles in HPV-OPSCC remain elusive; these include the glucocorticoid-induced leucine zipper (GILZ), Annexin-A1 and serum glucocorticoid-regulated kinase-1 (SGK-1)." (PMID 37954869, 2023). "Genes like SGK1, COP1, and CDC27 promote cell proliferation and regulate apoptosis in cancer cells." (PMID 37794118, 2023).